SLC3A1 (solute carrier family 3 member 1)
Description:
Acts as a chaperone that facilitates biogenesis and trafficking of functional transporter heteromers to the plasma membrane (By similarity). Associates with SLC7A9 to form a functional transporter complex that mediates the electrogenic exchange between cationic amino acids and neutral amino acids, with a stoichiometry of 1:1. SLC7A9-SLC3A1 transporter has system b(0,+)-like activity with high affinity for extracellular cationic amino acids and L-cystine and lower affinity for intracellular neutral amino acids. Substrate exchange is driven by high concentration of intracellular neutral amino acids and the intracellular reduction of L-cystine to L-cysteine. SLC7A9-SLC3A1 acts as a major transporter for reabsorption of L-cystine and dibasic amino acids across the brush border membrane in early proximal tubules. Associates with SLC7A13 to form a functional complex that transports anionic and neutral amino acids via exchange or facilitated diffusion. SLC7A13-SLC3A1 may act as a major transporter for L-cystine in late proximal tubules, ensuring its reabsorption from the luminal fluid in exchange for cytosolic L-glutamate or L-aspartate (By similarity).
Synonyms: NBAT; rBAT; CSNU1; D2H; ATR1
Tractability: Small molecule: a structure with a bound ligand is known. Antibody: UniProt places it where antibodies can reach, with high confidence; its Gene Ontology location is reachable by antibodies, with high confidence; UniProt predicts a signal peptide or a membrane-spanning region. PROTAC: its protein half-life has been measured.
Gene: Protein-coding gene on chromosome 2 (44,275,458 to 44,321,494, forward strand). Ensembl gene ENSG00000138079.
Subcellular location: Cell membrane; Apical cell membrane
Subcellular location (Human Protein Atlas): Mitochondria; Nuclear bodies
Pathways (Reactome):
Disease: Defective SLC3A1 causes cystinuria (CSNU); Defective amino acid transport by SLC7A9 causes cystinuria (CSNU)
Transport of small molecules: Amino acid transport across the plasma membrane
Gene Ontology:
Molecular function: protein binding; protein heterodimerization activity; amino acid transmembrane transporter activity; basic amino acid transmembrane transporter activity; L-cystine transmembrane transporter activity; L-amino acid transmembrane transporter activity; protein-containing complex binding
Biological process: amino acid transport; basic amino acid transport; L-cystine transport; aspartate transmembrane transport; basic amino acid transmembrane transport; carbohydrate metabolic process; gene expression; L-glutamate transmembrane transport
Cellular component: brush border membrane; extracellular exosome; plasma membrane; transmembrane transporter complex; apical plasma membrane; membrane; vacuolar membrane
Genetic constraint (gnomAD): Loss-of-function variants: 80 observed, 62.95 expected, observed/expected ratio (o/e) 1.27, 90% interval 1.06 to 1.53. The synonymous counts are far from expectation, so gnomAD's model fits this gene poorly and the ratio says little. Missense variants: 1,163 observed, 897.24 expected, observed/expected ratio (o/e) 1.3, 90% interval 1.23 to 1.36. Synonymous variants: 392 observed, 323.82 expected, observed/expected ratio (o/e) 1.21, 90% interval 1.11 to 1.32.
Gene-disease validity (ClinGen):
ClinGen rates the evidence that SLC3A1 causes each of these diseases.
cystinuria (autosomal recessive): Definitive. Cystinuria is a renal tubular amino acid transport disorder characterized by recurrent formation of kidneys cystine stones.
Homologues: Orthologues: chimpanzee SLC3A1 (99% identical), macaque SLC3A1 (96% identical), rabbit SLC3A1 (84% identical), pig SLC3A1 (82% identical), mouse Slc3a1 (80% identical), rat Slc3a1 (80% identical), guinea pig SLC3A1 (79% identical), dog SLC3A1 (79% identical), tropical clawed frog slc3a1 (56% identical), zebrafish slc3a1 (51% identical), Drosophila melanogaster Mal-B2 (30% identical), Drosophila melanogaster Mal-A4 (30% identical), and 10 more. Paralogues in human: SLC3A2 (21% identical), GBE1 (14% identical), AMY2A (13% identical), AMY2B (13% identical), AMY1A (13% identical), AMY1B (13% identical), AMY1C (13% identical).
Diseases named in the same sentence as SLC3A1 in open-access papers:
SLC3A1 is named in the same sentence as 67 diseases in open-access papers, as found by Europe PMC text mining. Sharing a sentence is not in itself a finding about the gene and the disease. The quoted sentences say what the papers report.
cystinuria (74 papers, 2012 to 2026). "In Australian Cattle Dogs (AUCDs), cystinuria was reported to be an autosomal dominant trait caused by a 6 bp deletion in the SLC3A1 gene (type II-A)." (PMID 41600767, 2026). "In the herein described case, the diagnosis of de novo cystinuria in the recipient was confirmed by the retrospective identification of a homozygous SLC3A1 mutation in the donor." (PMID 41333668, 2025). "Mutations in the SLC7A9 (also SLC3A1) gene are a common cause of cystinuria and lead to the formation of cystine stones." (PMID 40924792, 2025). "Cystinuria is caused by mutations in SLC3A1 and SLC7A9 genes, leading to defective cystine transport that result in stone formation typically beginning in the first two decades of life, with higher severity in males." (PMID 40786091, 2025). "Considering the significant sex bias of cystinuria and the implicated functions of male hormones, we performed an orchidectomy procedure on Slc3a1 KO male mice." (PMID 40110490, 2025). "Cystinuria occurs due to mutations in the solute carrier family 3 member 1 (SLC3A1) or the solute carrier family 7 member 9 (SLC7A9) gene that encodes the components of the cystine transporter." (PMID 37957454, 2024). "Mutations in different subunits SLC7A9 and SLC3A1 have been linked to cystinuria, an autosomal recessive disease characterized by the development of kidney stones." (PMID 39917180, 2024). "Four of the five patients (80%) with cystinuria-related gene SLC3A1 mutations were confirmed to have cystine stones." (PMID 37144129, 2023). "Cystinuria caused by mutations in SLC3A1 is classified as type A cystinuria, while mutations in SLC7A9 cause type B. Most patients with cystinuria carry two mutations (AA, BB, or AB)." (PMID 38114997, 2023). "Since the discovery of the underlying genetic defects in cystinuria, a number of variants in SLC3A1 and SLC7A9 have been reported to cause cystinuria." (PMID 37439839, 2023). "Cystinuria is a genetic disorder caused by defects in the b0,+ transporter system, which is composed of rBAT and b0,+AT coded by SLC3A1 and SLC7A9, respectively." (PMID 37439839, 2023). "While a number of variants have been discovered as a cause of cystinuria, interpretation of variants in SLC3A1 and SLC7A9 is still challenging." (PMID 37439839, 2023). "Our study updates the clinical and genetic spectrum of cystinuria, and we have comprehensively studied the genetic mutations in SLC3A1 that occurred in a Chinese family in which only a 12-year-old boy with thpe A cystinuria." (PMID 38114997, 2023). "We attempted to find a pattern for the association between the genotype of SLC3A1 variants and the manifestations of cystinuria in patients with different onset ages." (PMID 38114997, 2023). "In a cohort of Japanese cystinuria patients, mutations in SLC3A1 were found in around 10%, most of which were missense mutations." (PMID 38114997, 2023). "In summary, genetic testing revealed a nonsense mutation in the SLC3A1 gene in a patient with a stone composed of xanthine, which indicates the diagnosis of cystinuria." (PMID 37525149, 2023). "It is uncommon to find two frameshift mutations in SLC3A1 in Chinese cystinuria patients, and the deletion and insertion mutations in our study both caused frameshifts, but not a stop codon in the open reading frame." (PMID 38114997, 2023). "In our cohort, only one patient remained genetically uncharacterized for the cystinuria-causing mutation in the SLC3A1 and SLC7A9 genes." (PMID 38138969, 2023). "This includes the IGFBP5 gene candidate variant for bald thigh syndrome in sighthounds, SLC7A9 and SLC3A1 gene variants associated with cystinuria in Bulldogs, as well as PDK4 and TTN gene risk variants for dilated cardiomyopathy (DCM) in Dobermans." (PMID 36848397, 2023). "According to the mutation types of these two genes, Dello Strologo reclassified cystinuria into type A (two mutations on SLC3A1), type B (two mutations on SLC7A9), and type AB (one mutation on each of SLC3A1 and SLC7A9)." (PMID 37525149, 2023).
cystinuria (continued). "In summary, we report ten cystinuria cases and the interpretation of variants identified in SLC3A1 and SLC7A9, which included a novel variant in each gene." (PMID 37439839, 2023). "To date, studies on canine cystinuria have implicated variants in the functional candidate genes SLC3A1 and SLC7A9, encoding amino acid transporters involved in the excretion of cystine and known to explain approximately 70% of human cystinuria cases." (PMID 36848397, 2023). "Cystinuria is an autosomal recessive genetic disorder caused by two genes (i.e., SLC3A1 and SLC7A9)." (PMID 37115175, 2023). "A novel pathogenic heterozygous variant pair of the SLC3A1 gene was identified in a Chinese boy with type A cystinuria, enriching the mutational spectrum of the SLC3A1 gene." (PMID 38114997, 2023). "Researchers concluded that the cystinuria can be attributed to the heterozygous loss of SLC3A1; however, the exact role of the other affected genes has remained unclear in the development of the phenotype." (PMID 36313552, 2022). "Gene screens have found that mutations in SLC3A1 or SLC7A9 gene are responsible for most cases of cystinuria, for encoding defective cystine transporters." (PMID 36421847, 2022). "Two patients diagnosed with cystinuria were tested for the genetic mutations SLC3A1 and SLC7A9, respectively." (PMID 35612621, 2022). "Mice deficient for either the Slc3a1 or Slc7a9 gene develop cystine urinary stones, corresponding to similar stone types in human cystinuria." (PMID 35771811, 2022). "Findings from our study have clinical implications on the genetic screening of cystinuria and expand the mutation spectrum of SLC3A1, which would contribute to the progression of gene therapy for cystine stones." (PMID 36421847, 2022). "The first mutation detected in association with cystinuria in cats was the missense mutation in SLC3A1." (PMID 34438894, 2021). "A solute carrier family 3-member 1 (SLC3A1) variant was homozygous in a Greek cat presenting with cystinuria." (PMID 33785770, 2021). "In humans, cystinuria has been classified phenotypically into two types: Type A is caused by defects in SLC3A1 and is inherited in a true autosomal recessive manner, with heterozygotes having a normal urinary excretion of cystine." (PMID 34438894, 2021). "The heterodimeric b0,+AT-rBAT transporter encoded by the SLC7A9 and SLC3A1 genes, is also known as “cystine transporter”, based on its association with cystinuria detailed further below." (PMID 33302555, 2020). "According to gene-based classification, type A and type B cystinuria are associated with mutations of both alleles of SLC3A1 or SLC7A9, respectively." (PMID 33262960, 2020). "Solute carrier family 3 member 1 (SLC3A1) translates a type II membrane glycoprotein that encodes neutral amino acids associated with cystinuria." (PMID 32792959, 2020). "Inactivating mutations in the human SLC7A9 and SLC3A1 genes result in the partial failure of cationic amino acid reabsorption, clinically impressing as cystinuria." (PMID 33302555, 2020). "Patients with cystinuria as a result of SLC3A1 mutations are referred to as type A cystinurics and constitute approximately 55% of all cystinuric patients in the UK." (PMID 29696300, 2019). "Based on genotyping, cystinuria can be classified as Type A (caused by mutations in SLC3A1) or Type B (caused by mutations in SLC7A9)." (PMID 31878022, 2019). "Mutations in the gene encoding a renal amino acid transporter (SLC3A1, or the rBAT protein) have been identified in most patients with cystinuria establishing the most common cause of the disease termed cystinuria type I." (PMID 31221135, 2019). "So far, two genes have been implicated in the genesis of cystinuria: Solute Carrier Family 3 Member 1 (SLC3A1) and Solute Carrier Family 7 Member 9 (SLC7A9)." (PMID 30450686, 2019). "Loss-of-function of the amino acid transporter SLC3A1 has been associated with cystinuria (OMIM 220100)." (PMID 31679053, 2019).
cystinuria (continued). "While solute carrier family 3 member 1 (SLC3A1) is proposed to be a cysteine transporter, mutations in SLC3A1 lead to cystinuria, suggesting it instead transports cystine." (PMID 31100816, 2019). "Patients with cystinuria as a result of SLC3A1 mutations are referred to as type A cystinurics and constitute approximately 31% of all cystinurics." (PMID 29696300, 2019). "Cystinuria is an inherited metabolic disease that is caused by defects in two genes, SLC3A1 and SLC7A9, which result in a renal reabsorptive defect of cystine and other dibasic amino acids, including ornithine, arginine, and lysine." (PMID 28166740, 2017). "Molecularly, mutations in the SLC3A1 gene cause type A cystinuria, while type B is due to SLC7A9 gene mutations." (PMID 28166740, 2017). "No significant clinical differences were detected in this study between type A (SLC3A1 variants) and type B cystinuria (SLC7A9 variant)." (PMID 28166740, 2017). "For both genes, there is a clear difference in the distributions between the mutations known to be associated with cystinuria and the variants only found in ExAC (p = 1.69e-10 for SLC3A1, and p = 2.078e-06 for SLC7A9, Wilcoxon rank sum test)." (PMID 28812535, 2017). "We also compare these mutations that have been reported to cause cystinuria with the natural variation of SLC3A1 and SLC7A9 present in the large population study of genetic variation ExAC." (PMID 28812535, 2017). "After reporting on the first variant in the SLC3A1 gene causing cystinuria in a DSH cat, we subsequently examined 7 additional cystinuric cats of different breeds and from different geographical areas." (PMID 27404572, 2016). "In humans, dogs and mice, cystinuria is caused by variants in one of two genes, SLC3A1 and SLC7A9, which encode the rBAT and bo,+AT subunits of the bo,+ basic amino acid transporter system, respectively." (PMID 27404572, 2016). "Human cystinuria is genetically heterogeneous with 169 SLC3A1 (Type A) and 121 SLC7A9 (Type B) variants found thus far in human patients (HGMD database accessed on April 2016), respectively." (PMID 27404572, 2016). "The lack of a genotype/phenotype correlation has led to propose a genetic classification for cystinuria defined as type A if mutations are found in SLC3A1, type B if mutations are found in SLC7A9 and type AB when one mutation is found in each gene." (PMID 26359869, 2015). "Cystinuria caused by mutations in SLC3A1 (rBAT) has an autosomal recessive inheritance pattern (OMIM 600918) and mutations in SLC7A9 (b0,+AT) follows a partially autosomal dominant inheritance pattern (OMIM 220100)." (PMID 26359869, 2015). "Cystinuria is an autosomal recessive disease caused by the mutation of either SLC3A1 gene encoding for rBAT (type A cystinuria) or SLC7A9 gene encoding for b0,+AT (type B cystinuria)." (PMID 25048459, 2014). "Mutations in SLC3A1 are generally associated with type I cystinuria, but with the dupE5E9 exceptions exist; heterozygote carriers of this mutations show an increased urinary cystine excretion pattern." (PMID 22480232, 2012). "In contrast to the association of SLC3A1 mutations with cystinuria, variants restricted to PREPL causing an “isolated hypotonia” phenotype have not yet been reported." (PMID 22480232, 2012). "So far, two genes responsible for cystinuria have been identified: SLC3A1 (chromosome 2p21) encodes the heavy subunit rBAT of a renal b0,+ transporter while SLC7A9 (chromosome 19q12) encodes its interacting light subunit b0,+AT." (PMID 22480232, 2012). "- AA (homozygosity for one or compound heterozygosity for two SLC3A1 mutations) is mainly consistent with an autosomal recessive inheritance of cystinuria." (PMID 22480232, 2012). "Cystinuria is caused by pathogenic mutations in the genes that encode a common transporter made up of two subunits (rBAT, encoded by the SLC3A1 gene, and b0,+AT, encoded by the SLC7A9 gene), which leads to impaired cystine and dibasic amino acid reabsorption in the kidney tubules." (PMID 41282358, 2025).